TP73 (tumor protein p73)
Diseases named in the same sentence as TP73 in open-access papers (continued):
Sharing a sentence is not in itself a finding about the gene and the disease.
cancer (102 papers, 2004 to 2025). A tumor composed of atypical neoplastic, often pleomorphic cells that invade other tissues. "Overall, understanding the intricate crosstalk between STAT3, Pol III activity, TP73, and miR-106a-5p provides valuable insights into the molecular mechanisms underlying cancer pathogenesis and unveils potential targets for precision medicine interventions." (PMID 40725945, 2025). "Dysregulation of this axis has been implicated in various cancers, where aberrant expression of miR-106a-5p or TP73 contributes to tumor development, progression, and therapy resistance." (PMID 40725945, 2025). "Studies have revealed that TP73+/− mice display a heightened susceptibility to cancer, underscoring the undeniable association between p73 and cancer." (PMID 38933923, 2024). "Taken together, we believe that the current results contribute to a better understanding of the pathogenesis not only of ATL, but also many types of cancer associated with TP73, and particularly with TP73 SVs." (PMID 37864123, 2023). "In previous research reports, TP73 G4C14-A4T14 polymorphism has been associated with the occurrence of numerous cancers." (PMID 35073920, 2022). "The product of the TP73 gene, p73, has been associated with chemosensitivity, and its TA isoforms were upregulated in cancer cell lines by DNA damaging antitumor agents and paclitaxel." (PMID 36461044, 2022). "Beside somatic mutations, a polymorphism C4C14-to-A4T14 at exon 2 of TP73 has been described in several cancers." (PMID 33671606, 2021). "TP73 is rarely mutated in human cancers but found to be frequently over-expressed in several types of human cancer." (PMID 34204113, 2021). "We emphasize how TP73’s ability to control neurodevelopment and neurodifferentiation is co-opted in cancer cells toward neoneurogenesis, an emerging cancer hallmark, whereby tumors promote their own innervation." (PMID 34650986, 2021). "While the TP73 gene itself is rarely mutated in cancer, it exerts its oncogenic activities by abundant expression of distinct isoforms." (PMID 33339112, 2020). "On the contrary, several studies indicated that high TP73 expression was associated with clinical progression in human cancers." (PMID 31332036, 2019). "Tumor protein p73 (TP73) has been reported to be dysregulated in various types of human cancer and associated with clinical progression and outcome." (PMID 31332036, 2019). "TP73 gene is rarely mutated in cancers and p73 protein is often inactivated by binding to oncogenic partners including MDM2, MDM4, ΔNp73, or mutant p5323." (PMID 30886745, 2019). "All in all, TP73 G4C14-A4T14 polymorphism causes an upgrade cancer risk, especially in Caucasian population." (PMID 30420492, 2018). "In conclusion, our meta-analysis had successfully elaborated that TP73 G4C14-A4T14 polymorphism causes an upgrade cancer risk, especially in Caucasian population." (PMID 30420492, 2018).
cancer (continued). "G4C14-A4T14 polymorphism of TP73 gene has been reported with a potential association in cancer risks through affected cell homeostasis; however the results were not consistent." (PMID 30420492, 2018). "These genes related to the selected probes are mostly associated with cancer and LN metastasis, such as TP73, PDX1, FUT8, HOXD1, NMT1, and SEMA3E." (PMID 28951630, 2017). "According to the genomic locations, the 20 probes were associated to 39 genes including well-known cancer-related genes, such as TP73, PDX1, and FUT8." (PMID 28951630, 2017). "The genes that showed the highest variation in methylation, distal-less homeobox 5 (DLX5) and tumour protein 73 (TP73), are genes that are both linked to cancer development." (PMID 26220712, 2015). "Various TP73 variants have been identified to be highly expressed in several cancers." (PMID 38933923, 2024). "Additionally, accumulating evidence has proved the dysfunction of TP73 (tumor protein p73) was associated with the proliferation and prognosis of different cancers." (PMID 35250881, 2022). "Thereby, the modulation of the p73 network may help overcome chemoresistance in human cancers, as the inactivation of the TP73 gene is associated with an increased chemoresistance." (PMID 34769241, 2021). "On the other hand, for researchers, other polymorphisms of TP73 should be focused on to assess whether they change cancer risks." (PMID 30420492, 2018). "However, the TP73 gene is rarely mutated or deleted in human cancer, suggesting a more complicated scenario for the role of p73 in cancer." (PMID 26375672, 2015). "In the field of molecular medicine, the miR-106a-5p/TP73 axis has garnered significant interest due to its implications in cancer biology and therapeutic potential." (PMID 40725945, 2025). "Total TP73 knockout mice show developmental abnormalities, and TP73+/− heterozygous mice develop cancers." (PMID 41153767, 2025). "In human cancers, higher levels of TP73 in breast cancer tissue compared to normal breast tissue have been reported." (PMID 41153767, 2025). "Recent studies on TP73 have demonstrated that alternative splicing leads to the isoform switch from TAp73α to TAp73γ, significantly impacting cancer progression." (PMID 40227619, 2025). "Reports indicate that TP73 has roles in cell cycle arrest, apoptosis, and genome stability in multiple cancers." (PMID 38933923, 2024). "Super-enhancers have been found in genes involved in T-cell activation (IL2RA/CD25, CD30, and FYN) and known cancer genes (TP73, CCR4, TIAM2, NFATC1, NFATC2, and PIK3R1) in ATL cells." (PMID 38791169, 2024). "TP73 gene is mapped to a region on human chromosome 1p36 that is frequently deleted in neuroblastoma and other tumors, thus linking its role to cancer." (PMID 37650871, 2023). "In this regard, CRISPR was used to introduce TP73 exon 13 (E13) skipping in human cancer cell lines and in mice." (PMID 36631448, 2023). "We showed that deletion of E11 in TP73 leads to isoform switch from p73α to p73γ in both human cancer cells and mice." (PMID 37650871, 2023). "Other transcription factors (TP73, ERBB4, TBX5 and RUNX3) detected variations across cell lines, with TP73 being notably upregulated in four cancer lines except for SqCC/Y1." (PMID 35000271, 2022).
cancer (continued). "Secondly, to assess the TP73 function in pan-cancer and HNSC, survival analyses were conducted, including KM analysis, univariate, multivariate Cox regression analysis, as well as nomogram plots." (PMID 35756491, 2022). "Since the low expression of TP73 in cancer is regulated by DNA methylation and histone modification, TP73 is considered a good therapeutic target for cancer." (PMID 36358786, 2022). "These tools in combination with expression and molecular studies, have allowed to uncover the roles of TP73 in cancer and beyond, such as neurodevelopment, ciliogenesis, and metabolism." (PMID 34650986, 2021). "Generally, the clinical significance of TP73 expression had obvious difference depending on the type of human cancers." (PMID 31332036, 2019). "Further work on defining the setting of TP73 expression under cellular and pathological conditions will be pivotal for designing and implementing effective therapeutic regimen for cancer." (PMID 31852961, 2019). "We also studied the effect of DNA methylation on the expression TP73 in various neoplastic tissues and cancer cell lines." (PMID 31852961, 2019). "Our results in the DNA methylation study showed that hypermethylation within the TP73 promoter activates TP73 gene expression in cancer cells." (PMID 31852961, 2019). "Generally, immunohistochemical staining TP73 was suggested to be high levels in most types of human cancer." (PMID 31332036, 2019). "The expression of tumor protein p73 (TP73) in cancer cells suggests that it is positively correlated with tumorigenesis." (PMID 31852961, 2019). "We also examined differential expression of TP73 in colorectal cancer tissues based on major cancer stages, metastasis, and BMI." (PMID 31090204, 2019). "In silico analysis was managed to demonstrate the relationship of TP73 expression correlated with cancer tissues." (PMID 30420492, 2018). "The feature selection procedure extracted several cancer-related and lymph node metastasis-related genes, such as TP73, PDX1, FUT8, HOXD1, NMT1, and SEMA3E." (PMID 28951630, 2017). "We found alterations in DNA methylation related to age for 803 unique genes, most corresponding to coding genes known to be involved in cancer (e.g., TP73, CDKN1A and ESR1)." (PMID 29383109, 2017). "Because TP73 was reported to be commonly silenced by promoter hypermethylation in cancers, we proceeded to check if the p73 up-regulation by PRIMA-1 was mediated by demethylation." (PMID 27533450, 2016). "According to PubMeth, DAPK1, PYCARD, RB1, and TP73 are methylated in at least half of our fourteen cancer models." (PMID 19402918, 2009). "TP73 has roles in neurodevelopment, tissue homeostasis, and cancer." (PMID 41153767, 2025).
cancer (continued). "The TP73 gene, which is highly expressed in GB, gives rise to the TAp73 isoform, a pleiotropic protein that regulates neural stem cell biology; however, its role in cancer has been highly controversial." (PMID 39090849, 2025). "Although genetic variation in TP73 has been associated with various types of cancer, differential methylation of this gene is not well studied and its potential role during early development is not clear." (PMID 38418845, 2024). "However, the exact role of TP73 in radioresponse in human cancers is not well understood, even though its overexpression has been linked to reduced radioresistance in colorectal cancer." (PMID 37173692, 2023). "The radioresistance of cancer cells was blocked by TP73 overexpression or FOSB knockdown." (PMID 37173692, 2023). "As TP73 and TP63 are rarely mutated in cancers the analysis of the methylation status of P1 and P2 might contribute to our understanding of the resistance disease." (PMID 35806218, 2022). "Although TP73 gene is implicated in development of cancer, cancer epidemic patterns associated with TP73 polymorphisms (G4C14-A4T14) have not been fully elucidated." (PMID 35073920, 2022). "Firstly, an investigation of the TP73 gene in TCGA-pan-cancers and HNSC was conducted." (PMID 35756491, 2022). "TP73 was also upregulated in most cancer types, including CHOL, COAD, and THCA." (PMID 36479120, 2022). "In the same way, TP73, which is essentially never mutated in cancer, encodes numerous isoforms with two main subgroups differing in N-termini: the TAp73 isoforms and the N-terminally truncated ΔNp73 isoforms." (PMID 34680379, 2021). "However, this function has been a matter of controversy, fueled by the fact that inactivation of the TP73 gene is a very rare event in cancers involving chromosome 1p." (PMID 34368167, 2021). "Taking advantage of our previous work and experimental model, we proceeded to test the hypothesis that TP73 gene products are also involved in the cancer-neuronal crosstalk as upstream regulators of nervous system-related genes." (PMID 33339112, 2020). "Our data in this study showed that tumor protein TP73 expression is exclusive to cancer cells." (PMID 31852961, 2019). "Moreover, methylation-specific PCR and bisulfite sequencing studies revealed that TP73 promoter is activated only in cancer cell lines by DNA methylation." (PMID 31852961, 2019). "Similarly, TP73 is clearly involved in cancer, while the knockout studies indicate a clear involvement in metabolism, neuro-development and cancer progression." (PMID 30446632, 2018). "The most frequency genes are TP73 (both alleles loss) and PRDM16 (high copy gain) both are associated with late cancer stages which may cause uncontrolled cell division due to these genes changes." (PMID 30212456, 2018). "During cancer pathogenesis, TP73 may promote genomic instability, pro-proliferative signalling, evasion of growth suppression, activation of invasion and metastasis, angiogenesis, immune evasion, altered cellular energetics, neoneurogenesis, and cytotoxic therapy resistance." (PMID 41153767, 2025).
cancer (continued). "As PD-L1 expression is commonly used as a criterion for determining whether cancer patients should undergo ICI treatment, we examined the correlation between PD-L1/PD-1 expression levels, risk scores, and the expression of EPGN, LCN10, and TP73." (PMID 38933923, 2024). "Therefore, we also analyzed the expression of TEADs and TP73 in pan-cancer." (PMID 36479120, 2022). "Indeed, first of all, there are no evidences that TP73 gene deletion is causally associated to cancer, and only a very small percentage of human tumors (less than 1%) bear p73 mutations." (PMID 21391908, 2011). "The activities of SREBF1 and FOXA1 were higher in the primary cancer samples, while the activities of FOXC1 and TP73 were higher in normal samples, and the activities of transcription factors such as FOXA3 were higher in the CRPC samples." (PMID 39988626, 2025). "As per the QPCR array data, Rapamycin is believed to induce apoptosis in cancer cells by altering the components of the extrinsic (CD40LG, DAPK1, LTA, TNFRSF21) and intrinsic (BIRC5, BNIP3) apoptotic pathways as well as the TP73 upstream modulator." (PMID 38276004, 2024). "However, the direct influence of TP73 on chemoresistance in human cancers remains largely unknown." (PMID 37173692, 2023). "Within the set of genes that have a low standard deviation in all six-cancer types the genes that consistently have a lower expression relative to each other are EIF2B1, TP73 andSTX10." (PMID 31831960, 2019). "The expression of TP73 is specific to the cancer cell line and not to the neighboring normal liver tissue." (PMID 39764438, 2024). "Among these genes, TP73, GNAS, and NOTCH1 are notable ones with known relations to cancer." (PMID 33711952, 2021). "Furthermore, we found known (e.g. TP73, NTRK1, and CDC25C) and novel cancer biomarkers at the multi-cancer, cancer type and cancer subtype levels." (PMID 32152446, 2020). "To confirm the elevated expression of TP73 gene in tumorigenesis, we analyzed the TP73 protein level in human normal liver tissues and liver non-cancerous (Cancer-adjacent tissue) and cancerous tissues of HCC patients by immunohistochemistry." (PMID 31852961, 2019). "The results show that TP73 expression is exclusive to the cancer cell lines and not the adjacent normal liver tissues." (PMID 31852961, 2019). "Surprisingly, the results show that TP73 only expresses in cancer cell lines albeit to varying levels but not in normal liver stem cells (HepCY and HepCO) or in normal foreskin human fibroblast cell line (HS27)." (PMID 31852961, 2019). "After reviewing titles and abstracts, we excluded 1537 publications not investigating the association between TP73 G4C14-A4T14 polymorphism and cancer risk." (PMID 30420492, 2018).